MICAL2 (microtubule associated monooxygenase, calponin and LIM domain containing 2)
Description:
Methionine monooxygenase that promotes depolymerization of F-actin by mediating oxidation of residues 'Met-44' and 'Met-47' on actin to form methionine-sulfoxide, resulting in actin filament disassembly and preventing repolymerization. Regulates the disassembly of branched actin networks also by oxidizing ARP3B-containing ARP2/3 complexes leading to ARP3B dissociation from the network. Acts as a key regulator of the SRF signaling pathway elicited by nerve growth factor and serum: mediates oxidation and subsequent depolymerization of nuclear actin, leading to increase MKL1/MRTF-A presence in the nucleus and promote SRF:MKL1/MRTF-A-dependent gene transcription. Does not activate SRF:MKL1/MRTF-A through RhoA.
Synonyms: Mical-cL; MICAL-2; KIAA0750; MICAL2PV1; MICAL2PV2; MICALCL; FLJ14966; Ebitein1
Tractability: Small molecule: a structure with a bound ligand is known. PROTAC: ubiquitination databases record sites on it; its protein half-life has been measured.
Gene: Protein-coding gene on chromosome 11 (12,094,008 to 12,362,140, forward strand). Ensembl gene ENSG00000133816.
Subcellular location: Nucleus; Cytoplasm
Subcellular location (Human Protein Atlas): Cytosol; Nucleoplasm; Plasma membrane
Gene Ontology:
Molecular function: actin binding; F-actin monooxygenase activity; oxidoreductase activity; protein binding; FAD binding; mitogen-activated protein kinase binding; oxidoreductase activity, acting on paired donors, with incorporation or reduction of molecular oxygen, NAD(P)H as one donor, and incorporation of one atom of oxygen; NAD(P)H oxidase H2O2-forming activity
Biological process: actin filament depolymerization; cytoskeleton organization; positive regulation of transcription by RNA polymerase II; actin cytoskeleton organization; heart development; heart looping; sulfur oxidation
Cellular component: nucleoplasm; nucleus; cytoplasm
Genetic constraint (gnomAD): Loss-of-function variants: 72 observed, 122.52 expected, observed/expected ratio (o/e) 0.59, 90% interval 0.49 to 0.71. The upper end of that interval is the gene's LOEUF score, 0.71, which puts it in group 2 of 6, group 1 being the genes least tolerant of losing a copy. Missense variants: 1,324 observed, 1,466.5 expected, observed/expected ratio (o/e) 0.9, 90% interval 0.86 to 0.94. Synonymous variants: 562 observed, 571.89 expected, observed/expected ratio (o/e) 0.98, 90% interval 0.92 to 1.05.
Homologues: Orthologues: chimpanzee MICAL2 (99% identical), dog MICAL2 (91% identical), macaque MICAL2 (90% identical), rabbit MICAL2 (89% identical), guinea pig MICAL2 (89% identical), mouse Mical2 (86% identical), rat Mical2 (85% identical), tropical clawed frog mical2 (69% identical), zebrafish mical2b (57% identical), zebrafish mical2a (48% identical). Paralogues in human: MICAL3 (51% identical), MICAL1 (33% identical), DST (15% identical), MACF1 (14% identical), SPTBN1 (14% identical), SPTBN2 (14% identical), SYNE1 (14% identical), SPTB (14% identical), PLEC (13% identical), SPTBN4 (13% identical), SYNE2 (12% identical), SPTBN5 (12% identical), and 24 more.
Diseases named in the same sentence as MICAL2 in open-access papers:
MICAL2 is named in the same sentence as 49 diseases in open-access papers, as found by Europe PMC text mining. Sharing a sentence is not in itself a finding about the gene and the disease. The quoted sentences say what the papers report.
gastric cancer (9 papers, 2016 to 2024). A primary or metastatic malignant neoplasm involving the stomach. "In the present study, we investigated the relationship between MICAL2 and β-catenin intracellular distribution in gastric cancer cells and explored the underlying mechanism, aiming to determine their importance as predictors of gastric cancer cell metastasis." (PMID 36064550, 2022). "To confirm the role of MICAL2 in the regulation of cell migration, we performed MICAL2 loss-of-function assays in gastric cancer cells." (PMID 36064550, 2022). "The aim of this study was to explore the effects of MICAL2 on gastric cancer cell migration and determine the underlying molecular mechanisms." (PMID 36064550, 2022). "Overall, the in vitro and in vivo data strongly suggested that MICAL2 is highly expressed in human gastric cancer samples and is associated with poor clinical outcome." (PMID 34650666, 2021). "Next, we used both gain- and loss-of-function assays to alter MICAL2 contents and confirm its role in the regulation of gastric cancer cell proliferation." (PMID 34650666, 2021). "The precise mechanism underlying the MICAL2/MRTF-A-induced activation of CDC42 in gastric cancer cells requires further investigation." (PMID 33842533, 2021). "In contrast to previous findings indicating that MICAL2 is highly expressed in several other types of cancer, in the present study, we found that MICAL2 is highly expressed in gastric cancer cells and is associated with gastric cancer cell proliferation." (PMID 34650666, 2021). "In the present study, we found that MICAL2 was highly expressed in gastric cancer tissues, and this high expression level was associated with carcinogenesis and poor overall survival in gastric cancer patients." (PMID 34650666, 2021). "Similarly, our identification of microtubule-associated monooxygenase, calponin, and LIM domain containing 2 (MICAL2)_rs10831776 as risk factors is consistent with previous research showing elevated MICAL2 mRNA expression in gastric cancer tissues." (PMID 39408230, 2024). "In conclusion, we identified a novel role for MICAL2 in the regulation of gastric cancer cell migration, and showed that the underlying mechanism involved the impaired binding of E-cadherin to β-catenin in the cytoplasm, subsequently leading to the accumulation of β-catenin in the nucleus." (PMID 36064550, 2022). "However, to the best of our knowledge, the effects of MICAL2 on gastric cancer cell migration and the putative underlying molecular mechanisms remain largely unknown." (PMID 36064550, 2022). "Overall, these data indicated that MICAL2 expression is upregulated in gastric cancer at both the mRNA and protein levels, and this increased expression might be associated with poor prognosis among gastric cancer patients." (PMID 36064550, 2022). "To uncover the potential mechanism through which MICAL2 silencing induces E-cadherin degradation, we tested β-catenin/E-cadherin complex formation in gastric cancer cells." (PMID 36064550, 2022). "Next, the effect of MICAL2 depletion on gastric cancer cell migration was evaluated by transwell assay." (PMID 36064550, 2022). "The knockdown of MICAL2 significantly attenuated migratory ability and β-catenin nuclear translocation in gastric cancer cells while LiCl treatment, an inhibitor of GSK3β, reversed these MICAL2 knockdown-induced effects." (PMID 36064550, 2022). "We further compared MICAL2 expression between gastric cancer tissue from the TCGA-STAD cohort and normal samples in the Genotype-Tissue Expression (GTEx) database combined with adjacent TCGA-STAD tissue samples (controls), and obtained similar results." (PMID 36064550, 2022). "Further advances in our understanding of the function of MICAL2 will likely have important implications for the treatment of gastric cancer." (PMID 36064550, 2022). "Overall, these findings demonstrated that MICAL2 promotes E-cadherin degradation and gastric cancer cell migration in a Cdc42 activity-dependent manner." (PMID 36064550, 2022).
gastric cancer (continued). "Here, our data suggested that the MICAL2/MRTF-A complex promotes gastric cancer cell migration through the CDC42 pathway, at least partially." (PMID 33842533, 2021). "We found that ectopic expression of MICAL2 in gastric cancer cells increased MRTF-A accumulation in the nucleus, which was accompanied by enhanced MMP9 transcription and CDC42 activation." (PMID 33842533, 2021). "We showed that CDK6 and cyclin D protein levels were markedly downregulated in MICAL2-knockdown gastric cancer cells, whereas MICAL2 overexpression elicited the opposite effect." (PMID 34650666, 2021). "We then also evaluated the effect of MICAL2 on gastric cancer cell proliferation using CCK-8 and EdU staining assays." (PMID 34650666, 2021). "In this study, we have identified a pathway that contributes to MICAL2-mediated gastric cancer cell proliferation involving YAP nuclear translocation." (PMID 34650666, 2021). "In contrast, our results showed that MICAL2 overexpression resulted in a significant increase in Cdc42 activation in gastric cancer cells." (PMID 34650666, 2021). "Collectively, our results showed that MICAL2 has a promotive effect on gastric cancer cell proliferation through ROS generation and Cdc42 activation, both of which independently contribute to YAP dephosphorylation and its nuclear translocation." (PMID 34650666, 2021). "MICAL2 is highly expressed in multiple tumors, including gastric cancer, non-small cell lung cancer, and prostate cancer." (PMID 33842533, 2021). "Combined, these findings demonstrated that Cdc42 activation is required for MICAL2-mediated YAP nuclear translocation in gastric cancer cells." (PMID 34650666, 2021). "The immunohistochemical analysis showed that MICAL2 protein levels were significantly higher in gastric cancer tissues than in adjacent normal tissues (P < 0.05)." (PMID 34650666, 2021). "We found that MICAL2 overexpression-stimulated gastric cancer cell proliferation was attenuated in siYAP-transfected cells, while YAP overexpression reversed the inhibitory effect of siMICAL2 on cell proliferation." (PMID 34650666, 2021). "In the present study, we showed that EGF- or serum-induced cell migration was greatly diminished after MICAL2 depletion, suggesting that MICAL2 plays a key role in the migration of gastric cancer cells." (PMID 33842533, 2021). "Recent study showed that MICAL2-positive cells peculiarly localized at the primary human gastric cancer invasive front and MICAL2 knock-down in cancer cells resulted in mesenchymal to epithelial transition." (PMID 27430308, 2016). "As expected, MICAL2 expression was higher in gastric cancer cells than in control cells." (PMID 36064550, 2022). "In this study, we found that MICAL2 is highly expressed in gastric cancer tissues." (PMID 36064550, 2022). "To investigate whether MICAL2 was associated with the pathogenesis and progression of gastric cancer in humans, we first assessed whether any correlation existed between the MICAL2 expression level and clinical parameters in gastric cancer." (PMID 36064550, 2022). "A recent study showed that MICAL2 is a key inducer of ROS production in gastric cancer cells." (PMID 36064550, 2022). "Similarly, MICAL2-induced ROS generation has also been reported to enhance the migratory potential of gastric cancer cells." (PMID 35501725, 2022). "Furthermore, MICAL2 facilitates gastric cancer cell migration by promoting MRTF-A-dependent activation of cell division control protein 42 homolog (CDC42) and expression of MMP9." (PMID 33842533, 2021). "In summary, MICAL2 plays an important role in facilitating gastric cancer cell migration." (PMID 33842533, 2021). "Our results are of importance for understanding the pathophysiological role of MICAL2 in cancer cell proliferation and highlight that targeting MICAL2 may represent a novel intervention strategy for inhibiting gastric cancer progression." (PMID 34650666, 2021).
gastric cancer (continued). "Then we explored whether the mRNA and protein levels of MMP9 were also well correlated with MICAL2 or MRTF-A in gastric cancer cells." (PMID 33842533, 2021). "When we analyzed the role of Cdc42 in the maintenance of E-cadherin stability in gastric cancer cells, we observed that a constitutively active form of Cdc42 significantly abrogated the upregulation of E-cadherin expression and the downregulation of cell migratory potential in MICAL2-depleted cells." (PMID 36064550, 2022). "We next tested whether MICAL2 modulates the expression of EMT markers in gastric cancer cells." (PMID 36064550, 2022). "Moreover, we identified a novel link between MICAL2 and β-catenin in the regulation of gastric cancer cell migration, namely, that MICAL2 maintains Wnt/β-catenin signaling activation by promoting β-catenin nuclear localization, thereby enhancing the migratory ability of gastric cancer cells." (PMID 36064550, 2022). "Ectopic expression of MICAL2 augmented MRTF-A levels in the nucleus, and promoted the activation of CDC42, MMP9 expression, and gastric cancer cell migration." (PMID 33842533, 2021). "In the present study, we examined the effects of MICAL2 on MRTF-A nuclear localization and the expressions of migration-related proteins in gastric cancer cells." (PMID 33842533, 2021). "Collectively, these data indicated that ROS generation by MICAL2 promotes EGF-induced MRTF-A nuclear import and gastric cancer cell migration." (PMID 33842533, 2021). "MICAL2 is known as an oncogene in many cancers, such as pancreatic, ovarian, and gastric cancers, while there is no related research on thyroid cancer." (PMID 39872516, 2024). "Next, we analyzed the expression of MICAL2 in three gastric cancer cell lines (BGC-823, MGC-803, and SGC-7901) and a non-malignant gastric epithelial cell line (GES-1; control) by immunoblotting." (PMID 36064550, 2022). "MICAL2 protein levels were also analyzed in a tissue microarray containing 30 paired gastric cancer and adjacent nontumor tissues." (PMID 34650666, 2021). "We next tested whether MICAL2 modulates YAP expression and subcellular localization in gastric cancer cells." (PMID 34650666, 2021). "Our data establish a novel relationship between MICAL2 and MRTF-A in the context of the regulation of cancer cell motility, that might be involved in facilitating gastric cancer progression." (PMID 33842533, 2021). "As MICAL family members have a similar structure, we hypothesized that MICAL2 might promote YAP nuclear translocation via ROS generation and/or Cdc42 activation, thereby promoting gastric cancer cell proliferation." (PMID 34650666, 2021). "Our results suggested that the function of MICAL2 in gastric cancer cell proliferation is mediated through YAP rather than an ERK- or NF-κB-dependent mechanism." (PMID 34650666, 2021). "Next, MICAL2 protein levels were further analyzed by immunoblotting in the gastric cancer cell lines BGC-823 and SGC-7901 and the nonmalignant gastric epithelial cell line GES-1." (PMID 34650666, 2021).
prostate carcinoma (8 papers, 2012 to 2025). A carcinoma that arises from epithelial cells of the prostate gland. "MICAL2 prostate cancer variants (MICAL2-PV) are found to be overexpressed in prostate cancer, and the protein expression of MICAL2-PV is associated with prognosis in patients with colorectal cancer." (PMID 34868922, 2021). "MICAL2 is a monooxygenase that promotes depolymerization of F-actin, and has also been associated with progression of prostate cancer." (PMID 24950699, 2014). "MICAL1 has not been studied in prostate cancer but variants of MICAL2 have progression promoting role in prostate cancer." (PMID 36809527, 2023). "The genes ITGBL1, DSC3, COL4A6, ANGPT1, ARMCX1, MICAL2, and EPHA5 have been recognized as pivotal genes that substantially affect the microenvironment of prostate cancer." (PMID 40943497, 2025). "Concerning MICAL2, which codes for a RAB1 effector, this gene has been previously shown to be up-regulated in prostate cancer and to be necessary for prostate cancer cell viability." (PMID 22724020, 2012).
breast carcinoma (7 papers, 2016 to 2025). "MICAL2-deficient breast cancer cells develop marked migration defects through the inhibition of P38/HSP27/cytoskeleton signaling." (PMID 34650666, 2021). "The present study was a continuation of our previous work in which we demonstrated that the P38/HSP27/cytoskeleton signaling pathway is selectively responsible for MICAL2-induced breast cancer cell invasion." (PMID 34650666, 2021). "Specifically, through immunohistochemistry, the expression of the MICAL2 protein was highlighted in ECs of neo-angiogenic capillaries branching off within the tumor mass of gastric, kidney, and breast carcinoma, glioblastoma, and cardiac myxoma." (PMID 34946600, 2021). "We recently reported that MICAL2 potentiates breast cancer cell migration via maintaining epithelial growth factor receptor (EGFR) stability, leading to the activation of the P38/HSP27/actin pathway downstream of EGFR." (PMID 33842533, 2021). "We have previously reported that MICAL2 is involved in the regulation of breast cancer cell migration through the suppression of EGFR degradation." (PMID 33520979, 2020). "Further, we also reported that MICAL2 is expressed in neo-angiogenic endothelial cells (ECs) in human solid tumors (gastric, kidney and breast carcinoma, glioblastoma, and cardiac myxoma), and in animal models of ischemia/inflammation neo-angiogenesis, but not in the normal capillary bed." (PMID 34946600, 2021). "Interestingly, MICAL2 was down-regulated in epithelial-like breast cancer cells MCF7 and T47D, but up-regulated in breast cancer cells with mesenchymal features MDA-MB 231, BT-549 and HS578T." (PMID 26689989, 2016). "In particular, in breast cancer, cell migration is potentiated through maintaining epidermal growth factor receptor (EGFR) stability and activating EGFR/P38 signaling, whereas in gastric cancer cells the MICAL2/MRTF-A complex promotes migration through the CDC42 pathway." (PMID 34946600, 2021).
ovarian carcinoma (4 papers, 2016 to 2026). A malignant neoplasm originating from the surface ovarian epithelium. "Our data also show increased expression of MICAL2, a tumor-promoting factor regulating cellular growth and axon guidance signaling that has been implicated in ovarian cancer through Wnt/β-catenin pathway." (PMID 34455105, 2021). "Silencing of RUNX1 reduced EMT and increased apoptosis via the FOXO1-Bcl2 axis while MICAL2 silencing suppressed ovarian cancer proliferation and migration, promoting a MET." (PMID 41282576, 2026). "Wnt/β-catenin signaling has been reported to play an important role in MICAL2-induced EMT in ovarian cancer cells." (PMID 36064550, 2022). "While this work was in submission, it was published that MICAL-LIKE2, a protein of the MICAL family that shares sequence homology with MICAL2 but lacks the aminoterminal mono-oxygenase domain, is over-expressed in ovarian cancer and when silenced induces MET in ovarian cancer cells." (PMID 26689989, 2016). "Among these, RUNX1 and MICAL2 have been shown to regulate survival, EMT programs, and proliferation in ovarian cancer, rescpectively." (PMID 41282576, 2026).